TTR (transthyretin)
Diseases named in the same sentence as TTR in open-access papers (continued):
Sharing a sentence is not in itself a finding about the gene and the disease.
cardiomyopathy (continued). "Progressive accumulation of misfolded proteins such as Aβ, wild-type transthyretin (TTR), and PSN-1 results in the development of cardiomyopathy and HF in AD patients." (PMID 39967593, 2025). "The liver-synthesized TTR is primarily responsible for most ATTR manifestations, such as neuropathy and cardiomyopathy." (PMID 39044869, 2024). "There are two main types of CA, namely transthyretin (TTR) cardiomyopathy (ATTR-CM) and light chain (AL) cardiomyopathy (AL-CM)." (PMID 38068302, 2023). "The mean (±SD) number of genes per panel was 33±25, including 8±0.3 sarcomere genes, 4±2 storage cardiomyopathy, and RASopathy genes (LAMP2, PRKAG2, TTR, GLA, PTPN11, RIT1, and RAF1) and 22±23 other genes (range, 0–75)." (PMID 30681346, 2019). "TTR deposition is frequently observed in elderly individuals (22–25%) at autopsy, though it does not always lead to cardiomyopathy." (PMID 40283481, 2025). "While vitreous amyloid deposits have not been reported in patients with ATTRwt cardiomyopathy, vitreous ATTR in patients with heterozygous ATTRv contains both variant and wild type TTR deposits." (PMID 38410247, 2024). "Diflunisal, a nonsteroidal anti-inflammatory agent that stabilizes the TTR tetramer, has not yet been associated with a relevant effect on ATTR cardiomyopathy." (PMID 31083399, 2019). "TTR-FAP is a multi-symptom disease that may present with peripheral neuropathy (sensory and motor), autonomic neuropathy, gastrointestinal impairment, cardiomyopathy, nephropathy, or ocular deposition." (PMID 23425518, 2013). "A family history of cardiomyopathy in one or more first degree relatives was reported in four patients without a TTR mutation, and a family history of CTS in one or more first degree relatives was reported in eight patients without a TTR mutation." (PMID 35959393, 2022). "The patient in Box 1 illustrated that TTR-FAP may have a much more indolent and benign course than is commonly expected, and that distinctive features such as dysautonomia or cardiomyopathy may be minimal or absent." (PMID 32493526, 2020).
transthyretin amyloidosis (157 papers, 2012 to 2026). "PGG disaggregated fibrils formed by V30M and wild-type (WT) TTR, which are linked to hereditary Transthyretin Amyloidosis (ATTR) (ATTRv) and ATTRwt, respectively." (PMID 41492466, 2026). "Hereditary transthyretin amyloidosis (ATTRv) is a rare, autosomal dominant, inherited disease caused by variants in the gene encoding the transthyretin (TTR) protein." (PMID 41871624, 2026). "Background and Objectives: Hereditary transthyretin amyloidosis (ATTRv), a multisystemic disorder caused by transthyretin (TTR) gene mutations, exhibits phenotypic heterogeneity that can hamper recognition in non-endemic areas." (PMID 42195160, 2026). "This study revealed that patients with hereditary transthyretin amyloidosis exhibit significant nerve enlargement, detectable by ultrasound, not only in symptomatic individuals but also in presymptomatic carriers of TTR variants." (PMID 41153229, 2025). "The in vivo, liver-directed GT for the treatment of Transthyretin Amyloidosis, which is a fatal disease resulting from mutation to the TTR gene and is characterised by progressive accumulation of misfolded transthyretin (TTR) in different tissues." (PMID 40143050, 2025). "This approach was used to treat transthyretin amyloidosis caused by mutations in the TTR gene, and demonstrated a significant reduction in serum TTR levels in clinical trials." (PMID 40268745, 2025). "Light chain amyloidosis evolves due to plasma cell dyscrasia, while transthyretin amyloidosis can be caused either by a pathogenic TTR gene variant (formerly hereditary TTR) or arise as an acquired disease of the elderly." (PMID 40649056, 2025). "Transthyretin amyloidosis (ATTR) is a rare disease caused by the extracellular accumulation of misfolded transthyretin (TTR) amyloid fibrils." (PMID 40948648, 2025). "So far, there are two ATTR subtypes namely age-related ATTR (ATTR wild type, ATTRwt) and hereditary transthyretin amyloidosis (ATTR variant, ATTRv)." (PMID 40765557, 2025). "Hereditary transthyretin amyloidosis (ATTRv) results from genetic mutations that destabilize transthyretin (TTR), leading to the formation of extracellular aggregates and amyloid fibrils." (PMID 40666113, 2025). "Electrochemical skin conductance values in healthy controls, patients with hereditary transthyretin amyloidosis, and asymptomatic carriers of TTR pathogenic variants." (PMID 41332956, 2025). "Another example is hereditary transthyretin amyloidosis, where misfolded transthyretin proteins aggregate and cause cytotoxicity in peripheral nerves and heart." (PMID 40964614, 2025). "Hereditary transthyretin amyloidosis (ATTRv, “v” for variant) is a disease caused by the systemic deposition of mutant transthyretin (TTR)." (PMID 40002660, 2025). "The first situation (namely, aging) results in the deposition of wild-type TTR (wtTTR) fibrils, causing a condition known as “wild-type transthyretin amyloidosis” (ATTRwt) (which was previously called “senile systemic amyloidosis”)." (PMID 39337457, 2024). "One of the most advanced approaches is the one developed for the treatment of Transthyretin Amyloidosis, an autosomal dominant condition resulting from mutations in the TTR gene, leading to transthyretin accumulation in tissues." (PMID 39246827, 2024). "In contrast with its physiological role, TTR is also associated with a set of disorders known as “transthyretin amyloidosis” (ATTR)." (PMID 39337457, 2024). "Transthyretin amyloidosis (ATTR) is a chronic condition caused by the misfolding of transthyretin monomers into fibrils, which most commonly accumulate in cardiac and/or peripheral nervous system (PNS) tissues." (PMID 38912115, 2024). "Hereditary transthyretin amyloidosis (ATTRv) is a progressive, genetic condition caused by pathological variants in the transthyretin (TTR)." (PMID 38720335, 2024).
transthyretin amyloidosis (continued). "Hereditary transthyretin amyloidosis (ATTRv, v for ‘variant’) is an adult-onset, autosomal-dominant disease, caused by pathogenic variants in the TTR gene, encoding the transthyretin protein." (PMID 38700599, 2024). "Hereditary transthyretin amyloidosis, caused by transthyretin gene mutations, progresses with systemic impact and often presents peripheral neuropathy." (PMID 39010205, 2024). "Pathogenic variants in the TTR gene are known to be associated with hereditary transthyretin amyloidosis, which is inherited in an autosomal dominant manner." (PMID 37335747, 2023). "Transthyretin amyloidosis (A-ATTR) is caused either by variants in the TTR gene (A-ATTRv) or by the aggregation of wild-type TTR protein (A-ATTRwt)." (PMID 37653545, 2023). "The most common hereditary form is transthyretin amyloidosis (ATTRv) caused by the misfolding of protein monomers derived from the tetrameric protein transthyretin (TTR)." (PMID 37059440, 2023). "Transthyretin amyloidosis is a hereditary incurable disease caused by misfolded transthyretin (TTR) proteins build-up mainly affecting the nervous and cardiac tissues." (PMID 37545694, 2023). "Transthyretin amyloidosis (ATTR) is a group of diseases caused by the deposition of insoluble fibrils derived from misfolded transthyretin, which compromises the structure and function of various organs, including the heart." (PMID 37892778, 2023). "Transthyretin amyloidosis is caused by deposition of TTR amyloid fibrils in various tissues; ATTRv is caused by autosomal dominant mutations in the TTR gene, while ATTRwt stands for wild type ATTR." (PMID 37059440, 2023). "Transthyretin amyloidosis is a rare disease caused by the abnormal accumulation of transthyretin (ATTR) with subsequent morphological and functional changes in infiltrated tissues." (PMID 38203499, 2023). "Variant transthyretin amyloidosis (A-ATTRv) is an autosomal dominant disease characterized by transthyretin-derived amyloid accumulation in various organs and tissues that leads to progressive dysfunction and eventually death." (PMID 37653545, 2023). "Hereditary transthyretin amyloidosis (ATTR amyloidosis) is a rare condition where a mutation in the transthyretin (ATTR) gene leads to systemic deposition of amyloid fibrils." (PMID 34991732, 2022). "Amyloid precursor proteins involved in CA are mainly immunoglobulin light chain (AL) and transthyretin (TTR), with two distinct transthyretin amyloidosis (ATTR) types, namely hereditary or mutated (also known as ATTRv, v for variant) and wild type (ATTRwt)." (PMID 35665045, 2022). "Materials and methods: Five patients who had been diagnosed with hereditary transthyretin amyloidosis and two asymptomatic carriers carrying TTR E61K gene mutation were reported." (PMID 36311011, 2022). "Hereditary transthyretin amyloidosis (ATTRv) represents a group of severe diseases with a broad spectrum of genotypes and phenotypes caused by transthyretin (TTR) gene mutations." (PMID 35833187, 2022). "A variety of genetic variants of transthyretin can lead to hereditary transthyretin amyloidosis, which shows different clinical symptoms, like age of onset and pattern of organ involvement." (PMID 36302762, 2022). "Onset of the progressively fatal disease Transthyretin Amyloidosis (ATTR) is associated with the amyloidogenic aggregation of the human transthyretin (TTR) protein." (PMID 36590917, 2022). "Hereditary transthyretin amyloidosis (ATTRv; v for “variant”) is an autosomal dominant, progressive, and life-threatening disorder caused by mutations in the transthyretin (TTR) gene." (PMID 36009100, 2022). "The TTR V142I variant associated with hereditary transthyretin amyloidosis (hATTR) is present in up to 4% of African American (AA) and 1% of Hispanic/Latinx (HL) individuals and increases risk for heart failure." (PMID 33467513, 2021).
transthyretin amyloidosis (continued). "We evaluated and included an additional gene (TTR) associated with hereditary transthyretin amyloidosis (hATTR), which has a common founder variant in African ancestry populations." (PMID 33546753, 2021). "Hereditary transthyretin amyloidosis (ATTRv, v for variant) is a severe, heterogeneous multisystem condition with prevalent peripheral nervous system impairment, due to mutations in the transthyretin (TTR) gene." (PMID 34071271, 2021). "Following its description by Andrade in 1952, the number of identified causative mutations in TTR for transthyretin amyloidosis has increased." (PMID 31001136, 2019). "Transthyretin amyloidosis (ATTR) is one of the most common forms of hereditary systemic amyloidosis caused due to abnormal accumulation of transthyretin protein (TTR) in various organs/tissues." (PMID 29593496, 2018). "Transthyretin amyloidosis is a systemic disorder caused by amyloid deposits formed by misfolded transthyretin monomers." (PMID 24767411, 2014). "Transthyretin (TTR) is a tetrameric protein that serves critical physiologic functions across multiple organ systems while also harbouring the potential pathogenic precursor of transthyretin amyloidosis (ATTR)." (PMID 40717228, 2025). "Genetic testing confirmed variant transthyretin amyloidosis (ATTR) with mixed phenotype." (PMID 40429539, 2025). "Indeed, patients who inherited the maternal TTR mutation manifested earlier symptoms of disease than those with an affected father in the first global observational survey of ATTRv (THAOS–Transthyretin Amyloidosis Outcome Survey)." (PMID 37869146, 2023). "TTR mutations result in transthyretin amyloidosis (ATTR) and that these mutations may also affect neurons and neurite outgrowth." (PMID 37238925, 2023). "Hereditary transthyretin amyloidosis (hATTR or ATTRv [variant]) is a rapidly progressive, debilitating, and ultimately fatal disease resulting from the accumulation of transthyretin (TTR) amyloid fibrils in peripheral nerves and various other organs and tissues throughout the body." (PMID 35908242, 2022). "Hereditary transthyretin amyloidosis is caused by pathogenic variants (ATTRv) in the TTR gene." (PMID 32500375, 2021). "Consequently, results have been returned for TTR variants associated with hereditary transthyretin amyloidosis (hATTR), a condition predominantly affecting African ancestry populations in the USA, with newly approved therapeutics to improve health outcomes." (PMID 33546753, 2021). "Pathogenic ClinVar two-star variants and APOL1 renal risk variants were identified across all these groups, including TTR rs76992529 associated with amyloidogenic transthyretin amyloidosis, otherwise known as autosomal dominant familial transthyretin amyloidosis (FTA)." (PMID 31797629, 2020). "The structure of TTR, with four monomers rich in β-chains in a globular tetrameric protein, accounts for the predisposition of the protein to aggregate in fibrils, leading to a rare and severe disease, namely transthyretin amyloidosis (ATTR)." (PMID 33212973, 2020). "Transthyretin amyloidosis (ATTR) is a progressive disease characterized by systemic deposition of transthyretin-derived amyloid." (PMID 41898867, 2026). "In fact, a 2019 autopsy series found that up to 25% of patients over 80 years with HFpEF had evidence of cardiac transthyretin amyloidosis (ATTR)." (PMID 41493762, 2026). "The main forms of CA include transthyretin amyloidosis (ATTR-CM; distinguished into a hereditary and wildtype form [ATTRv and ATTRwt]) and light-chain amyloidosis (AL)." (PMID 42031926, 2026). "Current treatments for transthyretin amyloidosis (ATTR) focus on stopping the misfolding of the TTR protein or reducing TTR production and treating the symptoms with cardiac medication, while systemic chemotherapy is the focus for light-chain amyloidosis (AL)." (PMID 42041978, 2026).
transthyretin amyloidosis (continued). "Transthyretin amyloidosis (ATTR) is a progressive multisystem disorder characterized by extracellular deposition of misfolded transthyretin fibrils, leading to neurological, cardiac, gastrointestinal, urogenital, sexual, and ophthalmological involvement." (PMID 41893055, 2026). "The first, a LNP system for intravenous administration, is exemplified by Patisiran, which targets transthyretin (TTR) mRNA to treat hereditary transthyretin amyloidosis (hATTR)." (PMID 41304838, 2025). "Transthyretin amyloidosis (ATTR) is a rare, yet progressive, disease that is caused by misfolded transthyretin (TTR) proteins." (PMID 41002621, 2025). "Transthyretin amyloidosis (ATTR amyloidosis) is a life-threatening disease characterized by the accumulation of amyloid fibrils composed of transthyretin (TTR)." (PMID 40429804, 2025). "Transthyretin (TTR), a transport protein synthesized primarily by the liver, plays a central role in transthyretin amyloidosis (ATTR)." (PMID 41010872, 2025). "The objective was to implement the novel therapy for the treatment of transthyretin amyloidosis (TA), a RD in which the protein transthyretin (TTR) is formed incorrectly, leading to deposits in organs." (PMID 41404110, 2025). "The first study of this kind targeted the gene that codes for the blood circulating protein transthyretin (TTR), which can cause transthyretin amyloidosis (ATTR)." (PMID 41202069, 2025). "Transthyretin amyloidosis (ATTR) is a progressive, often fatal, multisystem disease caused by the deposition of toxic misfolded transthyretin (TTR) as amyloid fibrils in tissues and organs throughout the body." (PMID 40848527, 2025). "Transthyretin amyloidosis, also known as ATTR amyloidosis, is caused by the progressive accumulation of misfolded transthyretin (TTR) protein in tissues, predominantly the nerves and heart." (PMID 40214585, 2025). "Transthyretin amyloidosis (ATTR) is a systemic disease characterized by the deposition of misfolded transthyretin (TTR) in various organs as amyloid fibrils." (PMID 41428134, 2025). "The TTR gene encodes a plasma transport protein, and its mutations are closely associated with hereditary ATTR (transthyretin amyloidosis)." (PMID 41154642, 2025). "Continual drug discovery efforts for transthyretin amyloidosis were made, resulting recent approval of several TTR gene-silencing agents in 2022 and anti-TTR monoclonal antibodies as well as small molecule stabilisers currently in clinical trial." (PMID 40367241, 2025). "Transthyretin amyloidosis (ATTR) is a condition defined by accumulation of insoluble transthyretin amyloid deposits in multiple organs, especially in the peripheral nerve and heart muscle." (PMID 38410247, 2024). "Recently, this strategy was clinically tested in patients with transthyretin amyloidosis (ATTR) using lipid nanoparticles (LNP) containing a CRISPR-Cas9 system targeting the aberrant transthyretin (TTR) in the liver." (PMID 38182795, 2024). "There are novel medications approved for the treatment of hereditary transthyretin amyloidosis (ATTRv), classified as transthyretin (TTR) stabilizers or gene silencers." (PMID 38720335, 2024). "Transthyretin amyloidosis (ATTR) is a severe and rare disease characterized by the progressive extracellular deposition of misfolded TTR proteins forming amyloid fibrils and causing irreversible organ damage." (PMID 39472905, 2024). "In hereditary transthyretin amyloidosis (ATTR), mutations in the TTR gene result in a variant TTR protein that is more prone to misfolding and aggregation." (PMID 38985360, 2024). "Transthyretin amyloidosis (ATTR) is a severe and rare disease characterized by the progressive deposition of misfolded transthyretin proteins, causing irreversible organ damage." (PMID 39472905, 2024). "In brain tissue of patients with hereditary transthyretin amyloidosis and central nervous system involvement, misfolded transthyretin (TTR) was found to accumulate in the leptomeninges." (PMID 38801464, 2024).